EZH2 (enhancer of zeste 2 polycomb repressive complex 2 subunit)
Diseases named in the same sentence as EZH2 in open-access papers (continued):
Sharing a sentence is not in itself a finding about the gene and the disease.
cancer (continued). "In the future, it is necessary to develop efficient, highly selective, and low-toxicity EZH2 inhibitors, which are an important target for cancer therapy." (PMID 36672374, 2023). "EZH2-targeted inhibitors based on synthetic lethal effects play an essential role in ARID1A mutant cancers." (PMID 38008753, 2023). "An emerging target therapy for cancer treatment in preclinical studies is the EZH2 lysine methyltransferase inhibitors, with great results especially in combination with radiotherapy or chemotherapy, such as cisplatin, gefitinib and tamoxifen." (PMID 36866275, 2023). "Overexpression of EZH2 (Enhancer of zeste homolog 2), a member of the polycomb proteins which is responsible for the tri-methylation of H3k27 and inactive chromatin state, is a marker of cancer initiation, progression, metastasis and targeted therapy." (PMID 36866275, 2023). "Conversely, when EZH2T367A was replaced by EZH2T367D in our rescue experiments, EZH2-depleted SW620 cancer cells showed a considerable rise in EZH2 protein and H3K27me3 levels, to even higher levels compared with EZH2 wild type." (PMID 37069142, 2023). "Some studies have reported that EZH2 is expressed highly in most SCLC cells, an oncogenic factor associated with cancer development." (PMID 37543653, 2023). "In midline diffuse glioma, repression of EZH2 in microglia induces an antitumor phenotype resulting in decreased cancer cell invasion capability, increased phagocytosis by microglia, and tumor cell death." (PMID 36647827, 2023). "Genetic and post‐transcriptional abnormalities in EZH2 are frequently observed in many cancer types, and EZH2 targets involved in chromatin remodelling are often used to develop strategies based on synthetic lethality." (PMID 38041544, 2023). "Differentially expressed genes (DEGs) driven by EZH2 is obtained as gene correlation network figure exhibited as “pathway in cancer” and “metabolic pathway” panel, as representatives." (PMID 37803297, 2023). "Therefore, the increase in EZH2 could play a role in the cancer predisposition of NF1 patients." (PMID 37145209, 2023). "Contrariwise, EZH2-mediated invasion of cancer cells is abolished in the presence of high levels of RKIP." (PMID 36765912, 2023). "Enhancer of zeste homolog 2 (EZH2) is a significant epigenetic regulator that plays a critical role in the development and progression of cancer." (PMID 36545914, 2023). "Accumulating evidence has revealed the key contributing role of EZH2 in increasing the resistance of numerous cancer cells to chemotherapeutic drugs such as 5-FU." (PMID 36759799, 2023). "This indicates that EZH2 cannot be used as a marker of transition from the dormant to aggressive cancer." (PMID 36769153, 2023). "Subsequently, several groups have independently demonstrated the potential of G9a and EZH2 combination therapy as a viable treatment strategy in numerous cancer types." (PMID 36896891, 2023). "The EZH2 inhibitor used was tazemetostat, which is currently in clinical trials for RCa treatment, among other cancer types." (PMID 37228649, 2023). "Most anti-cancer strategies focused on EZH2 targeting have assumed that EZH2 methyltransferase activity is the key oncogenic activity of this protein." (PMID 36906655, 2023). "Epigenetic regulators such as HDACs, DNMTs, and EZH2 have been confirmed to have significant potential as cancer treatment targets." (PMID 37964279, 2023). "Since the main role of overexpressed EZH2 in cancer is to suppress the expression of tumor suppressor genes, we predicted that the expression of the tumor suppressor gene can be recovered by EZH2 inactivation in RCCs." (PMID 36808829, 2023). "We explore the expression of EZH2 gene in pan-cancer tissues as well as normal tissues in The Cancer Genome Atlas (TCGA) RNAseq data set (TCGA)." (PMID 37803297, 2023). "To date, different types of EZH2 inhibitors have been developed and multiple clinical trials of drugs targeting EZH2 in different types of cancers are underway." (PMID 38008711, 2023).
cancer (continued). "Ligand-activated ERβ1 can suppress TNBC growth by acting as a molecular switch for the oncogenic effect of EZH2 and repurposes EZH2 to impart anti-cancer effects." (PMID 37936981, 2023). "EZH2-mediated epigenetic modifications have diverse consequences and play critical roles in various cellular processes, developmental disorders, cancer, and aging." (PMID 37445833, 2023). "GSK126 treatment has also been found to upregulate classic MHC I allotypes in a human head and neck cancer cell line, suggesting similar effects to EZH2 in human cancers." (PMID 38067396, 2023). "First, in the context of cancer metastasis, MALAT1 appears to instigate epithelial-to-mesenchymal transition (EMT) and enhance the metastatic potential of cancer cells through modulation of the EZH2-Notch1 signaling pathway." (PMID 38203269, 2023). "In other cancers, EZH2 has been reported to activate oncogenic pathways in a PRC2-independent manner." (PMID 37210576, 2023). "Inhibitors of the Polycomb Repressive Complex 2 (PRC2) histone methyltransferase EZH2 are approved for certain cancers, but realizing their wider utility relies upon understanding PRC2 biology in each cancer system." (PMID 36670102, 2023). "It has been well-established that EZH2 promotes cell survival, proliferation, epithelial-mesenchymal transition, invasion and drug resistance of cancer cells through downregulation of tumor suppressor genes expression and oncogenes upregulation." (PMID 37941056, 2023). "Among the 5 upregulated lncRNAs, H19 and Hotair have been reported as upregulation as well as scaffolds for Ezh2 in cancer cells." (PMID 37198149, 2023). "EZH2 is abnormally expressed in various cancers, boosting cancer cell motility, invasion, and proliferation via several routes." (PMID 36884182, 2023). "By using simple cell growth experiment, it showed that two types of cancer cells had higher proliferation rate in EZH2 transfected groups when compared to control groups." (PMID 37198697, 2023). "More intriguingly, much lower levels of EZH2 were detected in DCAF1-depleted SW620 cancer cells compared to mock-depleted control cells, and the observed reduction of EZH2 correlated well with the disappearance of EZH2T367p." (PMID 37069142, 2023). "EZH2 catalyzes the trimethylation of histone H3 at lysine 27 (H3K27me3) and is frequently upregulated in human cancers." (PMID 38275371, 2023). "Overexpression of EZH2 occurs frequently in various solid tumors and is correlated with poor prognosis, suggesting that there is a compelling rationale for targeting EZH2 in cancer." (PMID 37210576, 2023). "There is a growing body of evidence supporting the critical function of PTMs of EZH2 in cancer development." (PMID 37909018, 2023). "This dual functionality is reflected in the observation of EZH2 amplifications and deletions in different kinds of cancer, which have been validated through functional assays and in vivo models." (PMID 37664059, 2023). "Our analyses led to the identification of CDK1, CCNA2, CCNB1, AURKA, and EZH2 as signature genes involved in cancer stemness and progression." (PMID 37189841, 2023). "Recent studies revealed the EZH2 gene (histone methyltransferase) in modulating the cancer invasiveness and metastatic potential." (PMID 36980957, 2023). "This highlights the potential use of EZH2 inhibitors (EZH2i) to augment immunotherapies in these cancers for therapeutic benefit." (PMID 37858275, 2023). "Since EZH2 plays an important role in epigenetic regulation, its aberrant expression and activity modulated by lncRNAs are highly relevant to cancer and other diseases." (PMID 37325482, 2023).
cancer (continued). "Western blot analysis of cell lysates clearly indicated that a decrease in EZH2 protein levels and cancer cell growth rate after EZH2 knockdown cannot be restored by ectopically expressing EZH2T367A." (PMID 37069142, 2023). "Enhancer of zeste homolog 2 (EZH2) is an enzymatic catalytic subunit of PRC2 that is currently a hot research topic for cancer therapy." (PMID 36936420, 2023). "One epigenetic regulator that demonstrates such a dual role in cancer is the histone methyltransferase EZH2." (PMID 37664059, 2023). "Prior studies have reported that USP7 stabilizes EZH2 via deubiquitination in different types of adult cancers." (PMID 37762082, 2023). "Currently, there are several ongoing clinical trials of drugs targeting EZH2 in different cancer types." (PMID 37627320, 2023). "Meanwhile, it was found that the EZH2 target gene labeled with H3K27me3 by PRC2 in normal cells has a corresponding relationship with the abnormal hypermethylation gene in cancer cells." (PMID 36672374, 2023). "Subsequent studies have found that HOTTIP is highly expressed in almost all cancers and can recruit epigenetic factors such as EZH2 or directly insert DNA double strands to form R-loops to promote cancer development." (PMID 36750826, 2023). "Both EZH2 expressions were related to cancer-infiltration immunocytes and immune modulators in LUAD." (PMID 37069494, 2023). "At present, increasing evidence supports that EZH2 can also be regulated by post-translational modifications (PTMs) in the development of cancer." (PMID 36672374, 2023). "Aberrant EZH2 expression in cancers is due to genetic, transcriptional, post-transcriptional, and post-translational modifications." (PMID 37240229, 2023). "Consistent with this mechanistic role, DCAF1-mediated EZH2 phosphorylation leads to elevated levels of H3K27me3 and altered expression of growth regulatory genes in cancer cells." (PMID 37069142, 2023). "Although Ezh2 showed only a trend to be upregulated after LPS stimulation here, the clinical availability of Ezh2 inhibitors in the treatment of cancer makes Ezh2 an interesting target with an easy clinical translation." (PMID 36982437, 2023). "Delineating the specific role of Polycomb Repressive Complex 2 (PRC2) in various cancer systems is desirable as inhibitors for EZH2 inhibitors are approved for some cancers." (PMID 36670102, 2023). "Being an epigenetic modulator, EZH2 has a profound effect not only on cancer cells, but also on TME." (PMID 36900330, 2023). "In the present study, the structure, expression, genetic mutation, DNA methylation, protein phosphorylation, and prognostic significance of EZH2 in pan-cancer were investigated to elucidate the potential oncogenic mechanism in various cancers." (PMID 36545914, 2023). "EZH2 gene plays an important role in the proliferation, migration, invasion, apoptosis and cycle of cancer cells by regulating several important signaling pathways, such as Wnt, RAS, NF-κB and NOTCH." (PMID 37198697, 2023). "Our data support the notion that the combination of down-regulating SLFN11 via EZH2 inhibitor with chemotherapeutic reagents should be considered in multiple cancer types." (PMID 36775056, 2023). "The consequences of subcutaneous tumorigenesis among nude mice illustrated that cancer volume of nude mice within the si-EZH2 group was remarkably reduced than that of the si-NC group." (PMID 38048186, 2023). "Evidence shows that EZH2 in the cytoplasm is closely coupled to cancer stem cell properties, thus inhibition of cytoplasmic EZH2 induces antitumor activity in NSCLC." (PMID 37803297, 2023). "EZH2 overexpression is linked to EMT induction and the migration of cancer cells, including those in pancreatic, NSCLC, and prostate cancer." (PMID 37909018, 2023). "Different types of EZH2 inhibitors are under evaluation in ongoing clinical trials involving different cancer types." (PMID 36731467, 2023).
cancer (continued). "Recent research has revealed that numerous cancer cells exhibit EZH2 overexpression and aberrant regulation." (PMID 38008753, 2023). "Genetic disruption or pharmacological inhibition of EZH2 enhances NK cells’ cytotoxicity against cancer cells through induction of interleukin 15 receptor, beta (IL-15Rβ), and NKG2D expressions." (PMID 36627707, 2023). "Subsequent results suggested that EZH2 was positively correlated with DNA methylation in almost all cancers, especially in LGG (r=0.81, P=5 × 10−125), LIHC (r=0.8, P=1.4 × 10−85)." (PMID 36545914, 2023). "Overexpression of EZH2 protein has been shown in various malignant tumors, including carcinomas of the breast, lung, stomach, colon, pancreatobiliary tract, liver, thyroid gland, prostate, and bladder." (PMID 38146588, 2023). "The promise for the use of small molecular inhibitors to target UTX/KDM6B and EZH2 enzymes as an anti-fibrotic therapy is provided by the FDA-approved EZH2 inhibitor, tazemetostat, an oral treatment currently being used with cancer patients." (PMID 37476157, 2023). "All samples in the TCGA pan-cancer cohort were classified into low‐ or high‐expression subgroups for GSEA analysis according to the median expression value of EZH2." (PMID 36545914, 2023). "To test this, we depleted DCAF1 and EZH2 in SW620 cancer cells overexpressing DCAF1 and EZH2 by using a lentiviral shRNA infection system." (PMID 37069142, 2023). "EZH2 is considered to be a new target for cancer therapy and has been shown to be a downstream target gene regulated by SNHG6 in a variety of malignancies." (PMID 37004005, 2023). "For example, the phosphorylation of EZH2 at K307 by TAK1 in injured respiratory epithelium or at T487 by CDK in cancer triggered the switch from H3K27me3-dependent to -independent function." (PMID 37710230, 2023). "DCAF1-mediated EZH2T367p stimulates cancer cell growth via an accumulation of EZH2 protein and an activation of EZH2 enzymatic activity catalyzing H3K27me3." (PMID 37069142, 2023). "Beyond its canonical PRC2-dependent role, EZH2 also acts in a PRC2 complex or methyltransferase activity-independent manner in cancers." (PMID 36642705, 2023). "This study enhances our understanding of EZH2′s roles in mutant driven cancer and contributes a stronger molecular basis for developing and improving therapeutic interventions in EZH2 driven blood malignancies." (PMID 37511137, 2023). "Clinical trials have indicated that targeting EZH2 to treat specific types of cancers, either as monotherapy or as part of combination therapy, is highly promising." (PMID 38008711, 2023). "Consistent with its causal role in regulating RKIP expression, the expression of EZH2 is negatively correlated with RKIP expression in cancers." (PMID 36765912, 2023). "In considering drug development, there is also a focus on potential PRC2-independent roles for EZH2 in cancer." (PMID 37377616, 2023). "EZH2, a histone methyltransferase, contributes significantly to cancer cell survival and proliferation." (PMID 37760442, 2023). "Reduction in H3K27me3 and a concomitant increase in H3K4me3 are observed in promoters of genes involved in cAMP, WNT, and cancer pathways upon Ezh2 inhibition." (PMID 37572850, 2023). "By referring to related literatures and databases, E2F1, GLI1, CDK3, and Mcm4, as candidate target genes, were found to be closely related to the occurrence of cancers, which was very helpful to clarify the mechanism of EZH2 in PC." (PMID 37198697, 2023). "These PTMs can modulate EZH2 histone methyltransferase activity, localization, binding partners, and stability, affecting its role in cancer development and progression." (PMID 37909018, 2023). "The potential benefits of EZH2 inhibitors as cancer therapies are highlighted by the fact that inhibiting EZH2 decreases the proliferation of numerous cancer cell lines." (PMID 38275371, 2023).
cancer (continued). "Regarding EZH2 itself, the nature of its role in cancer and AML in particular appears complex and remains to be fully resolved, with uncertain implications for this enzyme as a therapeutic target in AML." (PMID 37035245, 2023). "According to the GEPIA2 online tool, the ubiquitously spread of EZH2 in multiple human cancer and normal tissues can be observed." (PMID 36545914, 2023). "In the current study, the oncogenic mechanism of EZH2 in various cancers was elucidated by investigating the structure, expression, genetic mutation, DNA methylation, protein phosphorylation, and prognostic significance of EZH2 in the TCGA pan-cancer samples." (PMID 36545914, 2023). "While EZH2 is highly expressed in embryonic stem cells and plays important roles in stem cell maintenance, elevated EZH2 expression has also been observed in multiple cancers, in particular, the more primitive and malignant types." (PMID 36766749, 2023). "Cellular lncRNA HOTAIR transcript, reported as a poor prognostic factor in cancers was detected particularly in the EZH2 immunoprecipitated samples corresponding to CEGBCs-DB compared to CEGBCs-BL." (PMID 37147437, 2023). "The gene E6/E7 promotes transcriptional activation and expression of EZH2 which further mediates cancer cell proliferation." (PMID 37131568, 2023). "Aberrant histone methylation has been observed in many human cancers, and the most well-known aberrations occur in enhancer of zeste 2 (EZH2), which is thought to be the main enzyme involved in histone modification." (PMID 36980741, 2023). "The levels of EZH2 in most cancers were markedly upregulated relative to those in the control tissues." (PMID 36884182, 2023). "Taken together, these results suggest that BMI1/RING1B degraders, such as MS147, but not the parent EED binder or EED/PRC2 degraders, can effectively suppress the proliferation of cancer cell lines that are insensitive to EZH2 knockout or EED/PRC2 degraders." (PMID 36737841, 2023). "Some studies reported that in ccRCC, EZH2 regulates kinase reprogramming, leading to sunitinib resistance, and is a cancer stem cell marker." (PMID 37747077, 2023). "EZH2 controls the coordinated inactivation of several tumor suppressor genes, thereby promoting cancer growth, invasion, and drug resistance." (PMID 36647827, 2023). "EZH2 has been shown to contribute to the progression of various cancers via different mechanisms of action." (PMID 36768289, 2023). "It has been widely recognized that EZH2 can be regulated in different kinds of human cancers at both the transcriptional and translational levels." (PMID 36672374, 2023). "In DCAF1-depleted SW620 cancer cells, ectopic EZH2 wild type and EZH2T367A phospho-blocking mutant showed low stead-state protein levels and minimal growth stimulatory effects." (PMID 37069142, 2023). "Mann-Whitney p values for staining percentages of EZH2 and p16 between the two carcinoma histotypes were 0.35 and 0.15, respectively." (PMID 38146588, 2023). "The EZH2 expression was observed to increase with increasing grades of carcinoma which was statistically significant (p = 0.001)." (PMID 37131568, 2023). "Mann-Whitney p values for EZH2 and p16 staining intensity between the two carcinoma histotypes were 0.37 and 0.26, respectively)." (PMID 38146588, 2023). "The role of EZH2 has been documented in pathogenesis of various carcinomas such as breast, lung, thyroid, and endometrial cancers." (PMID 37131568, 2023). "In this work, we provide an overview of the preclinical studies based on the combined application of cisplatin (a conventional chemotherapy agent) and EZH2 (Enhancer of Zeste Homolog 2) inhibitors (targeted epigenetics therapy) in different cancer types." (PMID 36230683, 2022). "Together with H3K36M, H3G34W/L and EZH2 mutant cancers, these data highlight a parallel mechanism for PcG domain expansion/invasion and blockade of differentiation pathways in distinct cancer types." (PMID 36105358, 2022).